CRP (C-reactive protein)
Diseases named in the same sentence as CRP in open-access papers (continued):
Sharing a sentence is not in itself a finding about the gene and the disease.
diabetes (continued). "Further adjustment for CRP, WCC and granulocyte count (model 3) had little impact, but excluding those with a history of heart attack, stroke and medication for hypertension (model 4) reduced the difference between those with and without diabetes for venular tortuosity." (PMID 35852586, 2022). "Participants with diabetes were on average older, had greater BMI, and demonstrated several metabolic characteristics of type 2 diabetes, including low HDL cholesterol, increased fasting insulin and elevated CRP levels when compared to participants without diabetes." (PMID 25607823, 2015). "However, this study excluded subjects with diabetes and hypertension and did not investigate the effects of pomegranate polyphenols on other notable biomarkers of oxidative stress and inflammation, such as oxidized LDL and C-reactive protein (CRP)." (PMID 23936637, 2013). "However, CRP is a non-specific biomarker of inflammation and is elevated in many chronic diseases typically seen in CAP cohorts, such as diabetes mellitus (DM) and advanced cancer." (PMID 38202252, 2023). "DM: diabetic; NDM: non-diabetic; T2DM: type 2 diabetes mellitus; ALT: alanine aminotransferase; HDL-C: high-density lipoprotein cholesterol; LDL-C: low-density lipoprotein cholesterol; CRP: C-reactive protein; VDBP: vitamin D binding protein." (PMID 33728195, 2021).
Obesity (2,570 papers, 2004 to 2026). Accumulation of substantial excess body fat. "In contrast, there were no significant indirect effects in the associations between irisin or adiponectin and obesity, abdominal obesity or sarcopenic obesity when CRP was examined as a mediator." (PMID 41457869, 2026). "Research indicates that the inflammatory response associated with obesity correlates with changes in plasma levels of C-reactive protein (CRP), interleukin-6 (IL-6), and other inflammatory biomarkers." (PMID 41590696, 2026). "CRP is commonly used as a blood inflammatory marker and is associated with chronic low-grade inflammation, such as that observed in obesity and metabolic syndrome." (PMID 41556049, 2026). "Next, we examined specific traits related to obesity and T2D of which 331, nine, and eight were associated with C-reactive protein (CRP), BMI and, blood lipids, respectively." (PMID 41547928, 2026). "There is well-established evidence demonstrating a physiological association between obesity and elevated levels of CRP." (PMID 41590696, 2026). "The evaluation of the obtained AUC values allowed to clearly highlight the superior discrimination performance of ACLI regarding the inflammatory markers hs-CRP and IL-6 in patients with overweight and obesity involved in dietary interventions for weight loss." (PMID 41899249, 2026). "Some inflammatory markers, such as C-reactive protein and interleukin-6, have been linked to deregulated neurohormonal circuits in both obesity and depression." (PMID 40292529, 2025). "Following SCI, total and truncal fat appear to be associated with cardiometabolic risk factors, including dyslipidemia, obesity, and elevated inflammatory markers, including IL-8 and CRP." (PMID 40781458, 2025). "The subgroup analysis on BMI revealed that overweight and obesity are associated with a reduced response to the most favorable effects of the supplementation, particularly in terms of suppressing CRP and IL-6 markers." (PMID 41022286, 2025). "Research related to the increase in CRP and IL-6 levels associated with obesity also validated the existence of immune cell infiltration in the obese population." (PMID 40612555, 2025). "In some studies, however, elevated concentrations of CRP are associated with specific abnormalities characterizing the metabolic syndrome (Mets), including obesity, low HDL‐C, high TG, and insulin resistance." (PMID 41497474, 2025). "The inverse association between 25(OH)D and hs-CRP further supports the anti-inflammatory role of vitamin D and its potential relevance in obesity-associated low-grade inflammation." (PMID 40710009, 2025). "Further, light and high activity levels were negatively associated with obesity and a high activity level was associated with lower CRP and higher HDL-cholesterol levels." (PMID 40635900, 2025). "The model highlights that obesity and inflammation are central risk factors, with BMI and CRP affecting cholesterol, triglycerides, and overall cardiovascular health." (PMID 41154955, 2025). "Obesity and higher levels CRP were associated with higher LV mass index, while the continuous use of bDMARDs during the study period was associated with lower LV mass index." (PMID 41141372, 2025). "Conversely, CRP is a key mediator and marker of the low-grade systemic inflammation that is a hallmark of obesity pathophysiology." (PMID 41404432, 2025). "Several studies have shown that elevated BMI is associated with higher CRP levels, indicating that obesity contributes to systemic inflammation through the release of inflammatory mediators by adipose tissue." (PMID 41289287, 2025). "Each 1 SD log increment in YKL-40 and CRP levels resulted in similarly increased risk estimates for obesity-related and gastrointestinal cancers." (PMID 40188292, 2025). "HIV infection is often accompanied by neutropenia, whereas obesity is associated with elevated neutrophil counts, higher C-reactive protein levels, and an increased neutrophil-to-lymphocyte ratio." (PMID 41305316, 2025).
Obesity (continued). "The association between hypertension, CRP, and cognitive impairment in individuals with obesity indicates a greater risk of cerebral vascular damage and neurodegeneration in those with generalized atherosclerosis." (PMID 40005412, 2025). "The elevated levels of circulating CRP in obesity are linked to an increased incidence of type 2 diabetes and cardiovascular diseases." (PMID 40218888, 2025). "While otherinflammatory markers, such as IL-6 and chemokines, are also important, CRP andNLR were chosen for this study due to their greater clinical accessibility,cost-effectiveness, and well-documented associations with both obesity anddepression." (PMID 40926826, 2025). "CRP has been considered a significant factor linked to obesity in two papers with a high level of evidence and with weight excess in one paper with a moderate and three with a low level." (PMID 40565251, 2025). "Within the depressed cohort, hypertension and obesity remained independently associated with higher CRP, whereas female sex and alcohol intake were linked to lower levels." (PMID 40943152, 2025). "In both subgroups, overweight or obesity was associated with significantly increased values of Castelli indices I and II, the TyG index, and approximately two-fold higher CRP concentrations." (PMID 41516208, 2025). "The Article describes a minipig model of obesity-associated meta-inflammation, characterized by increased C-reactive protein levels and white blood cells, together with changes in the expression of genes related to inflammation and metabolism." (PMID 40770069, 2025). "Several studies, including our own have demonstrated a strong association between elevated CRP levels and obesity, which is found to be more pronounced in women compared to men." (PMID 40463745, 2025). "As an acute-phase reactant to inflammation and infection, C-reactive protein (CRP) is associated with obesity along with inflammatory mediators such as TNF-α and IL-6." (PMID 40939575, 2025). "Obesity‐associated inflammation, characterized by increased CRP, IL‐6, leptin, and TNF‐α, further exacerbates endometrial cancer progression by enhancing cancer cell invasion and inhibiting apoptosis." (PMID 40922069, 2025). "First, the identification of obesity and inflammation (BMI and CRP) as central, modifiable risk factors points to these as primary intervention targets." (PMID 41154955, 2025). "In the lipedema group, we noticed significant positive association between DII of intervention diet and CRP level after dietary treatment; similarly in the overweight/obesity group." (PMID 41010539, 2025). "Elevated CRP was positively associated with known inflammatory risk factors such as diabetes, hypertension, smoking, obesity, and Black race." (PMID 40943152, 2025). "Cross-sectional and prospective assessment of the association of different measures of obesity (BMI, WC and %BF) and IL-6, CRP and adiponectin at 22 years of age, in a population-based Birth Cohort in Southern Brazil." (PMID 40717997, 2025). "Obesity also amplified CRP (adjusted ratio 3.48 versus normal weight), underlining the importance of controlling adiposity when interpreting CRP and periodontitis links." (PMID 41301163, 2025). "CRP, a marker of low-grade inflammation, has been linked to obesity, insulin resistance, vascular dysfunction, and atherosclerosis." (PMID 41301855, 2025). "Obesity has been associated with elevated uric acid, CRP, IR (low FGIR), and lower HDL levels that are in line with our results." (PMID 40136618, 2025). "They further suggested that not only epicardial fat but also subcutaneous fat depots, obesity, BMI, age, and C-reactive protein level (CRP)—a marker of systemic inflammation—are linked to AF." (PMID 40870855, 2025).
Obesity (continued). "Older age (OR = 1.04, 95% CI: 1.02–1.06), current smoking (OR = 1.76, 95% CI: 1.26–2.45), elevated CRP (1–3 mg/L: OR = 1.40, 95% CI: 1.04–1.87; ≥3 mg/L: OR = 1.63, 95% CI: 1.00–2.66), and obesity (OR = 8.29, 95% CI: 6.12–11.21) increased CMRC risk." (PMID 41301855, 2025). "Chronic low-grade inflammation is a hallmark of prediabetes and obesity, typically characterized by elevated levels of hs-CRP, IL-6, and TNF-α." (PMID 41228432, 2025). "For instance, besides being the most common risk factor for OSA, obesity has been shown to increase the levels of cytokines, including CRP and TNF-α." (PMID 40807193, 2025). "In this study involving people with obesity, an association was found between BMI and CRP and dietary inflammatory index scores." (PMID 39885337, 2025). "Both among women contemplating pregnancy and pregnant participants, we found obesity associated with CRP and IL-6, which is consistent with previous findings." (PMID 40920854, 2025). "LDG, compared with RDG, was identified as an independent risk factor for elevated CRP levels on POD 3 in patients with obesity." (PMID 40208467, 2025). "Obesity is strongly associated with HS, and if CRP can change due to these factors, how do we even know what is affecting its levels?" (PMID 41458786, 2025). "Given that CRP levels exceeding 2.0 mg/L are considered a risk-enhancing factor for cardiovascular disease, the CRP concentrations of our male participants with obesity can be classified as slightly elevated." (PMID 40219022, 2025). "The median CRP was highest in subjects with obesity and was within moderate risk in HPT subjects and subjects with dyslipidemia." (PMID 40299469, 2025). "In particular, it has been shown that the coexistence of PCOS and obesity is associated with elevated CRP." (PMID 40572700, 2025). "Traditional risk factors—such as age, obesity, hypertension, dyslipidemia, smoking, and alcohol use—as well as elevated C-reactive protein levels, were significantly associated with increased CVR." (PMID 40870513, 2025). "Their findings revealed that periodontitis led to elevated serum CRP levels in obese rats, underscoring the compounded impact of periodontitis on the systemic inflammation associated with obesity." (PMID 40422620, 2025). "Obesity was consistently found to have a significant adverse effect on all of the given metabolic risk factors, increasing the levels of CRP, HbA1c, triglycerides, and blood pressure, while decreasing the level of HDL-cholesterol." (PMID 40635900, 2025). "All patterns, except the Health-conscious pattern for women, had direct effects on obesity, indirect effects on all metabolic risk factors, and a total effect on CRP." (PMID 40635900, 2025). "Even though correlations are not as strong as established risk factors, e.g., BMI (r = 0.32 with CRP), they are comparable to strong predictors of obesity, such as pericardial fat and intrathoracic fat." (PMID 40647182, 2025). "A strong positive correlation was found between CRP and BMI (r = 0.67, P = 0.012), supporting its association with obesity-related inflammation." (PMID 41523554, 2025). "In this study, we determined that genetic predisposition to dentures causally related with obesity and CRP, established risk factors for EAA." (PMID 39003475, 2024). "For example, weight loss in individuals with obesity has been linked to a decrease in inflammatory markers including CRP." (PMID 39576692, 2024). "At baseline, obesity and steatosis were associated with increased serum concentrations of CRP, IL-6 and TNFα." (PMID 39200991, 2024). "A distinct predictor and potential risk factor for preeclampsia in women, the elevated CRP value, was found to have a strong correlation with pre-pregnancy obesity." (PMID 39280386, 2024). "Stratified by sex, obesity, and sensitivity c-reactive protein (hs-CRP) category, a statistically significant association was only shown in females, those without obesity, and those without hyper hs-CRP." (PMID 38297351, 2024).
Obesity (continued). "Our study found that the snack pattern had a significant indirect effect on the obesity risk of children by increasing CRP levels, but the total effect on the risk of childhood obesity was not significant." (PMID 39599620, 2024). "In lean individuals, a sedentary behavior is associated with enhanced systemic inflammation and C-reactive protein levels independent from obesity." (PMID 38425433, 2024). "This study aims to evaluate chronic inflammation in patients with obesity using hs-CRP, and its association with long-term weight loss outcomes after laparoscopic sleeve gastrectomy (LSG) and laparoscopic Roux-en-Y gastric bypass (LRYGB)." (PMID 39509008, 2024). "The mediation analysis showed that MetS-Z mediated the association between CRP levels and overall cancer (12.67%), digestive system cancer (10.16%), and obesity-related cancer risk (13.87%)." (PMID 38386717, 2024). "Our research showed that this pattern had a significant indirect effect on reducing the obesity risk in children by lowering CRP levels." (PMID 39599620, 2024). "The strength of this study is its use of mediation analysis to identify the potential role of CRP in the association between dietary patterns and obesity." (PMID 39599620, 2024). "Other conditions thought to be associated with moderate elevation of C-reactive protein levels are viral infections, low-grade mucosal infections (e.g., periodontitis), obesity, insulin resistance, depression, smoking, and mild alcohol consumption." (PMID 39000133, 2024). "In patients with overweight, the increased risk of death was nearly two-fold, whereas a 40% increased risk of death was seen in patients with high CRP and obesity, but the precision of the estimate was lower than in normal-weight and overweight." (PMID 38914635, 2024). "The positive correlation between CRP levels and these anthropometric measures suggests that higher levels of obesity are associated with increased systemic inflammation." (PMID 39473678, 2024). "Severe obesity is associated with a low-grade chronic inflammation, and high-sensitivity C-reactive protein (hs-CRP) is a marker that can be used to evaluate chronic inflammation status." (PMID 39509008, 2024). "Participants in this study exhibited baseline CRP levels of 5.07 ± 5.34 mg/L, indicative of low-grade inflammation, which is commonly associated with obesity." (PMID 39770957, 2024). "The current study shows that first trimester low plasma ferritin levels (as a proxy for low iron status), low hCG, high CRP, high IL-6 levels, higher age and obesity (BMI >30) were independently associated with IH." (PMID 38330593, 2024). "GI microbiome differences have been associated with C-reactive protein levels, resulting in increased inflammation and changes to intestinal permeability with outcomes such as obesity and Crohn’s disease." (PMID 39199837, 2024). "MCP-1 and IL-6 were associated with overweight and obesity (p = 0.01–0.01–0.04, respectively); IL-6 and IL-8 were positively correlated with fat mass and CRP serum levels (p = 0.02–0.04, respectively)." (PMID 38892570, 2024). "A meta-analysis comprising 51 cross-sectional studies also revealed that obesity was associated with an increased level of CRP." (PMID 39337223, 2024). "CRP better represents many chronic inflammation-related conditions such as obesity, DM, HT, atherosclerosis, and the risk of cardiovascular heart disease due to atherosclerosis." (PMID 38775535, 2024). "Numerous studies have extensively investigated CRP as an acute inflammatory biomarker in various populations and established it as a significant obesity-associated MetS predictor." (PMID 39765954, 2024). "In contrast, another systematic review (including 11 studies) demonstrated that the use of a low-energy diet in individuals with obesity was associated with lower CRP levels." (PMID 39769504, 2024). "Prior research has demonstrated that the association between obesity and CRP levels is particularly pronounced in women." (PMID 39519093, 2024).